GRPR (gastrin releasing peptide receptor)
Diseases named in the same sentence as GRPR in open-access papers (continued):
Sharing a sentence is not in itself a finding about the gene and the disease.
prostate carcinoma (continued). "More evidence and experience will be needed for the other candidate PET radiotracers (e.g., those targeted to prostate-specific membrane antigens, the gastrin-releasing peptide receptor, and others) in the imaging evaluation of prostate cancer." (PMID 26726317, 2015). "Elevated GRPR expression was found on the cell membrane of prostatic intraepithelial neoplasia, primary prostate cancer, invasive prostatic carcinoma, and androgen-independent human cancer cells as well as well-differentiated and metastatic prostate cancers." (PMID 26577829, 2015). "In this study, we report the oncogenic role of GRPR in different biological processes of prostate cancer progression through activation of specific targets involved in cancer-associated signaling pathways (including PI3K/Akt and JAK-STAT)." (PMID 26097883, 2015). "We show that overexpression of these GRPR targets is restricted to prostate carcinomas harbouring ERG and/or ETV1 rearrangements, establishing their potential as therapeutic targets for these particular molecular subsets of the disease." (PMID 26316886, 2015). "For instance, GRPR expression is greatly reduced during the dedifferentiation of prostate cancer cells from androgen-controlled to androgen-independent transformation." (PMID 25849333, 2015). "Gastrin-releasing peptide receptor (GRPR) is a cell membrane receptor expressed in almost all the prostate cancer (PC) primary tumors and, frequently, in metastases." (PMID 25036155, 2014). "Staining for PSMA was seen in 100% (17/17), EpCAM in 82.3% (14/17), VEGF in 82.3% (14/17) and GRPR in 100% (17/17) of prostate cancer specimens." (PMID 24727373, 2014). "In 11.8% (2/17) of cases, the GRPR staining intensity of prostate cancer was higher than stroma, while in 88.2% (15/17), the staining was equal." (PMID 24727373, 2014). "The current study is the first to present data on the expression of PSMA, EpCAM, VEGF and GRPR in locally recurrent prostate cancer after brachytherapy or external beam radiotherapy." (PMID 24727373, 2014). "GRPR seems to be overexpressed in prostate cancer in comparison to sparse expression in normal prostate tissue." (PMID 24727373, 2014). "Expression of the gastrin-releasing peptide receptor (GRPR) in prostate cancer suggests that this receptor can be used as a potential molecular target to visualize and treat these tumors." (PMID 24312607, 2013). "Prostate cancers with a higher GRPR density showed a better prognosis than ones with low or negative expression." (PMID 24312607, 2013). "Both 64Cu/NOTA-monomer and 64Cu/NOTA-dimer 2 are suitable for detecting GRPR-positive prostate cancer in vivo by PET." (PMID 22333272, 2012). "In prostate cancer, the GRPR expression has been tied to neoplastic transformation, cell migration, proliferation and invasion capacity." (PMID 22333272, 2012). "In this study, we investigated the potential benefits of dimeric BBN-based peptide radio-tracers for GRPR-mediated prostate cancer PET imaging." (PMID 22333272, 2012). "GRPR mRNA expression has also been detected in prostate tumors and tissues adjacent to prostate cancers." (PMID 22296774, 2012). "Some GPCRs have also been reported to be functionally involved in the cancer progression, such as gastrin-releasing peptide receptor (GRPR) in prostate cancer, CXCR4 in metastasis and so forth." (PMID 22715397, 2012). "GRPR is overexpressed on 84% of all human prostate cancers according to a study by Markwalder and Reubi." (PMID 22333272, 2012). "The presence of GRPR has been documented in small cell lung cancers, prostate cancers, breast cancers and others." (PMID 22333272, 2012). "Here, we report that BBS stimulates an increase in COX-2 mRNA, protein expression, and the release of PGE2 from the GRPR-positive, androgen-insensitive prostate cancer cell line, PC-3." (PMID 21745389, 2011). "In primary prostate cancer, low grade lesions are frequently GRPR‐rich." (PMID 39908060, 2025).
prostate carcinoma (continued). "αvβ3 integrin is often expressed in tandem with the GRPR on the surfaces of most prostate cancers." (PMID 40430268, 2025). "Furthermore, both BBN2 TMs have promoted specific eradication of both GRPR-expressing prostate cancer cell lines with high efficiency and in a comparable manner." (PMID 40141329, 2025). "In addition, GRPR-targeted PET imaging is particularly advantageous in prostate cancer cases where prostate-specific membrane antigen (PSMA) expression is heterogeneous or absent, providing a complementary targeting approach." (PMID 40775579, 2025). "Importantly, GRPr has been found to be expressed in multiple cancers, including small-cell lung cancer, prostate cancer, breast cancer, gastrinoma, and others, making it an attractive target for pan-tumor imaging." (PMID 40863874, 2025). "Interestingly, the density and incidence of NTS1R expression was found to increase in advanced and androgen-independent stages of prostate cancer, whereas GRPR-expression is more prominent in the early stages of the disease." (PMID 39339259, 2024). "This study successfully introduced multiple bis-deoxygalactosyl-carborane building blocks to a GRPR-selective ligand, resulting in conjugates carrying up to 80 boron atoms per molecule, which demonstrated successful internalisation into PC3 prostate cancer cells that express the GRPR." (PMID 39768156, 2024). "GRPR has also been shown to have elevated expression in lower-grade prostate cancers." (PMID 39456584, 2024). "GRPR has garnered significant interest in the fields of oncology and nuclear medicine due to its high-density expression in various cancers, including prostate cancer (PC), breast cancer (BC), small cell lung cancer (SCLC), gastrinoma, gastrointestinal stromal tumors, and other cancers." (PMID 38279185, 2024). "Toward this goal, we explored a first example of a combined application of [99mTc]Tc-DT11 (DT11, N4-Lys(MPBA-PEG4)-Arg-Arg-Pro-Tyr-Ile-Leu-OH; NTS1R-specific) and [99mTc]Tc-DB7(DB7, N4-PEG2-DPhe-Gln-Trp-Ala-Val-Gly-His-Leu-NHEt; GRPR-specific) in prostate cancer models." (PMID 39339259, 2024). "The authors concluded that GRPr and PSMA-based imaging may have a complimentary role to fully characterize prostate cancer disease, GRPr being targeted in low-metastatic-risk patients while PSMA could be a valuable target in higher risks." (PMID 35864350, 2023). "• GRPr-based imaging seems to play a complementary role to choline-based or PSMA-based PET/CT imaging in selected low- and intermediate-risk PCa patients for better characterization and eventually biopsy guidance of prostate cancer disease." (PMID 35864350, 2023). "In vitro studies including cytotoxicity studies, wound-healing assay, saturation and internalization experiments were carried out in prostate cancer cell lines expressing either PSMA (LNCaP cells) or GRPr (PC3 cells), to investigate their potential future use as SPECT/MRI diagnostic tools for PCa." (PMID 39380961, 2023). "GRPR targeting for the imaging of prostate cancer has been increasingly evaluated in recent years due to the limitations of the well-established PSMA targeting, which include PSMA-negative lesions, false-positive scans, and a degree of resistance to PSMA-targeted radionuclide therapy." (PMID 37175001, 2023). "In addition, GRPr-based imaging seems to play a complementary role to PSMA-based or Choline-based imaging for fully characterization of prostate cancer disease." (PMID 35864350, 2023). "Therefore, we have selected and evaluated GRPR as a potential target for diagnostics and therapeutics of prostate cancer." (PMID 37175001, 2023). "However, GRPr is also highly expressed in tumoral vessels of urinary tract cancers, particularly treatment-naïve and recurrent prostate cancer, and during early and advanced stages of PCa." (PMID 38201600, 2023).
prostate carcinoma (continued). "Furthermore, it also showed a biodistribution profile suitable for GRPR-positive prostate cancer imaging and acceptable dosimetry estimations when tested on animal models." (PMID 37175001, 2023). "Previous studies have shown the potential of using bispecific radioligands targeting PSMA and other overexpressed proteins, such as gastrin-releasing peptide receptor (GRPR), to improve tumor targeting and increase the detection sensitivity of prostate cancer imaging." (PMID 36770755, 2023). "When searching for an initial validation of AuNP-BBN-Pt as new tools for the image-guided and selective delivery of Pt(IV) prodrugs to tumor cells and tissues, we have focused on prostate cancer (PCa), as this type of cancer is known to overexpress GRPR in a relatively large percentage of cases." (PMID 36593794, 2023). "Since Doxil, liposomal DOX, was launched, researchers have continued the dynamic exploration of the field of liposomal and micellar formulations to search for further improvements, one of those being active targeting of GRPR-overexpressing tumors, such as prostate cancer or small-cell lung cancer." (PMID 36834867, 2023). "The radioconjugates [111In]In-DOTA-Tz-TCO-PEG4-AR, [111In]In-DOTAGA-Tz-TCO-PEG4-AR, [111In]In-DOTA-Tz-TCO-Pip-AR and [111In]In-DOTAGA-Tz-TCO-Pip-AR were studied to determine their uptake and internalization in a prostate cancer in vitro model using the well-established GRPR-positive cell line, PC3." (PMID 36559063, 2022). "Although optimal tumor-to-blood and tumor-to-kidney ratios might not yet have been reached due to the prolonged blood circulation, our probes are promising candidates for the preoperative and intraoperative visualization of GRPR-positive prostate cancer." (PMID 35057090, 2022). "Gastrin-releasing peptide receptors (GRPR) are overexpressed in prostate cancer (PCa)." (PMID 36077458, 2022). "The subtype GRPR is particularly relevant for the development of anticancer therapies and its overexpression has been reported in several cancer types such as small lung cell, head/neck squamous cell, colon, glioblastoma, breast and prostate cancer." (PMID 36559063, 2022). "The gastrin-releasing peptide receptor (GRPR), also known as bombesin receptor subtype 2, is a G-protein coupled receptor that is overexpressed in several solid cancers, such as breast, lung, and prostate cancer." (PMID 35951084, 2022). "In vitro, [66Ga]Ga-NOTA-PEG2-RM26 was characterized in GRPR-expressing PC-3 prostate cancer cells." (PMID 33574368, 2021). "As a consequence of the multitude of options for treatment of disseminated prostate cancer, late-stage patients have highly variable treatment histories that jeopardize good clinical evaluation of the most optimal timing of GRPR and PSMA imaging (and therapy) in these patients." (PMID 34830920, 2021). "The aim of the present study was to evaluate whether prostate cancer (PC) patients can be accurately classified on the bases of tissue expression of gastrin-releasing peptide receptor (GRPR) and prostate-specific membrane antigen (PSMA)." (PMID 33854977, 2021). "In addition to their use in diagnostics, PSMA and GRPR hold promise for the application of radionuclide therapy in the management of prostate cancer." (PMID 34830920, 2021). "Therefore, we conclude that [99mTc]Tc-maSSS-PEG2-RM26 can be used for imaging of GRPR-overexpression in prostate cancer in clinics a few hours after injection." (PMID 33573232, 2021). "Molecular imaging of the gastrin-releasing peptide receptor (GRPR) could improve patient management in prostate cancer." (PMID 33574368, 2021). "Further reports have shown that PSMA and GRPR PET/CT may have added value in evaluating biochemical recurrence of prostate cancer." (PMID 34830920, 2021).
prostate carcinoma (continued). "However, a phase I escalation study conducted in patients with metastatic castration-resistant prostate cancer was discontinued due to the severe adverse effects induced by GRPR activation after injection of therapeutic doses of [177Lu]Lu-AMBA." (PMID 34830920, 2021). "One crucial issue in the design of the dual-targeted complex presented in this study, aimed at the targeting of the mitochondria of GRPr-positive prostate cancer cells, was the presence of a triglycine linker between the BBN peptide and the organometallic fragment carrying the mitotropic group." (PMID 33467760, 2021). "Peptide-based radiopharmaceuticals targeting GRPR evaluated in human prostate cancer." (PMID 33335885, 2020). "Thus, the effects of GRP/GRPR signaling abrogation in inhibiting prostate cancer cell tumorigenicity result from diminishing the population of cancer-propagating cells." (PMID 32205838, 2020). "Targeting GRPR in oligometastatic prostate cancer could improve therapy output in early stages of prostate cancer." (PMID 33081166, 2020). "GRPR has emerged as an important target in a number of cancers including prostate cancer." (PMID 33081166, 2020). "Gastrin-releasing peptide receptor (GRPR) is overexpressed in the majority of prostate cancers." (PMID 33352838, 2020). "Competitive binding assays in prostate cancer PC3 cells showed that both nanoconstructs have a high affinity towards the GRPr; however, there was a significant contrast in the cell internalization behavior of the two radiolabeled nanoconstructs in the same cell line." (PMID 33375074, 2020). "GRPR is overexpressed in a variety of human cancer types including prostate cancers." (PMID 32533273, 2020). "GRPR, also known as bombesin receptor subtype 2, is a G-protein-coupled receptor mostly expressed in organs of the gastrointestinal tract and the pancreas but also in various cancers including breast and prostate cancer." (PMID 30823564, 2019). "Several studies reported that 63%–100% of prostate cancer samples are GRPR positive." (PMID 31340483, 2019). "The most exploited field of application of GRPR-targeting peptides is prostate cancer, although bombesin analogues might be relevant for other highly prevalent tumours." (PMID 30543050, 2018). "Consequently, a great number of promising GRPR-radioantagonists was developed and thoroughly studied in prostate cancer models." (PMID 29137110, 2017). "We have studied pyrazolyl-diamine 99mTc (I) tricarbonyl complexes containing acridine orange (AO) intercalators and bombesin (BBN) analogues, which provided specificity towards the gastrin releasing peptide receptor (GRPR) overexpressed in prostate cancer cells." (PMID 28211920, 2017). "Most anti-GRPR radiopeptides have been hitherto developed for treatment of prostate cancer." (PMID 29137110, 2017). "Finally, we show that overexpression of these GRPR targets is restricted to prostate carcinomas harboring ERG and/or ETV1 rearrangements, establishing their potential as therapeutic targets for these particular molecular subsets of the disease." (PMID 26097883, 2015). "In fact, several reports have described the effect of selective GRPR antagonists on inhibition of tumor growth in numerous models, including prostate cancer cell lines (PC-3, DU-145, MDA-PCa-2b), although the associated mechanisms are not yet completely understood." (PMID 26097883, 2015). "To evaluate whether GRPR could be involved in the phenotypic characteristics of advanced prostate cancer cells, we evaluated the impact of GRPR silencing in invasion potential and in the capacity to grow without attachment." (PMID 26097883, 2015). "In this study, we aimed to characterize the oncogenic role of GRPR in prostate cancer in an ETS context and to identify specific players involved in the GRPR pathway with potential to be used as therapeutic targets for this particular subset of prostate cancers." (PMID 26097883, 2015).
prostate carcinoma (continued). "Binding of GRPR stimulates the growth of prostate cancer cells in vitro and in vivo." (PMID 24727373, 2014). "The data concerning the high levels of receptor expression in prostate tissues, which are in the earliest phase of the malignant transformation process, suggest that GRPR expression can be a marker of choice for the early detection of prostate carcinoma and local metastases." (PMID 24312607, 2013). "Although the aberrant overexpression of COX-2, the BBS-like peptide, GRP, and GRPR has been documented for prostate cancers with NE features, particularly in the setting of recurrent disease, a mechanistic link between GRPR activation and COX-2 expression in prostate cancer cells has not been made." (PMID 21745389, 2011). "Therefore, GRPR expression has traditionally been associated with low-grade disease, as various GRP agonist and antagonist radioligands have shown promising results in the detection of early-stage prostate cancer." (PMID 39598482, 2024). "Another promising molecular target for the detection of PCa is the gastrin-releasing peptide receptor (GRPR), a 7-trans-membrane G-protein-coupled receptor activating phospholipase C-signalling, which has been shown to be overexpressed especially in breast and prostate cancer." (PMID 38668903, 2024). "Likewise, considering the high expression of GRPr in early stages of prostate cancer, this could also be a potential, clinical indication for [177Lu]Lu-RM2." (PMID 38201600, 2023). "Moreover, GRPR overexpression has been found in a large spectrum of human cancers including small-cell lung carcinoma, breast, stomach, colon and prostate cancer which renders it an appealing target for the development of novel peptide based radiopharmaceuticals for oncological applications." (PMID 38020178, 2023). "In addition, GRPr-based imaging can play a complementary role to choline-based or PSMA-based imaging for full characterization of prostate cancer disease and biopsy guidance in low- and intermediate-metastatic-risk PCa patients and has the potential to discriminate them from those of higher risks." (PMID 35864350, 2023). "GRPR could be used for imaging of prostate cancer spread due to its expression pattern." (PMID 33574368, 2021). "Likewise, in another approach, the GRPR and integrin αVβ3 associated with tumor angiogenesis have been concomitantly targeted by a dual PET tracer [68Ga]Ga-BBN-RGD enhancing diagnostic accuracy in breast and prostate cancer patients." (PMID 34830920, 2021). "The identification of GRPR as an important target for imaging and treatment of prostate cancers has led to the development of numerous GRPR-targeting radiotracers with the aim of improving the sensitivity for detecting prostate cancer and its distant metastases." (PMID 33573232, 2021). "The encouraging results obtained by the preclinical and the most recent clinical studies suggest that GRPR analogs, and in particular GRPR antagonists, might play in the future an essential role in the diagnosis of prostate cancer at different stages and in the treatment of mCRPC." (PMID 33809749, 2021). "The availability of radio-iodinated GRPR/PSMA bispecific heterodimers could provide an advantage for theranostics applications as they could be used for imaging of prostate cancers by SPECT and PET cameras with I-123 and I-124 labels, respectively, and for therapeutic purposes labeled with I-131." (PMID 31340483, 2019). "Therefore, targeting both PSMA and GRPR with an anti-GRPR/PSMA heterodimer may have a high clinical impact in the diagnostic imaging and therapy of prostate cancer." (PMID 31540122, 2019). "However, this dual-targeted PET radiotracer could only be used for noninvasive imaging of prostate cancer because GRPR was an important biomarker for prostate cancer." (PMID 30483904, 2018).